GNG5B (G protein subunit gamma 5B)
Description:
Guanine nucleotide-binding proteins (G proteins) are involved as a modulator or transducer in various transmembrane signaling systems. The beta and gamma chains are required for the GTPase activity, for replacement of GDP by GTP, and for G protein-effector interaction.
Synonyms: GNG5P2; GNG5ps; HG3L1; HG3L3; dJ364I1.1
Gene: Protein-coding gene on chromosome X (110,346,103 to 110,440,372, reverse strand). Ensembl gene ENSG00000133136.
Subcellular location: Cell membrane
Gene Ontology:
Molecular function: G-protein beta-subunit binding
Biological process: G protein-coupled receptor signaling pathway
Cellular component: heterotrimeric G-protein complex; plasma membrane
Homologues: Orthologues: mouse Gng5c (88% identical), zebrafish gng5 (78% identical), Drosophila melanogaster Ggamma1 (32% identical). Paralogues in human: GNG5 (94% identical), GNG10 (51% identical), GNG3 (47% identical), GNG2 (46% identical), GNG4 (46% identical), GNG12 (44% identical), GNG7 (44% identical), GNG8 (43% identical), GNGT2 (28% identical), GNG11 (26% identical), GNGT1 (25% identical).